AHR (aryl hydrocarbon receptor)
Diseases named in the same sentence as AHR in open-access papers (continued):
Sharing a sentence is not in itself a finding about the gene and the disease.
breast carcinoma (continued). "On the other hand, neither the synthetic ER ligand ICI 182,780 (ICI) nor raloxifene are significantly capable of activating AHR in OCs despite their ability to induce robust Cyp1a1 expression in breast cancer cells, suggesting that AhR agonist activity is both cell-type and agonist-type dependent." (PMID 33066667, 2020). "Similarly, in oral cancer and triple negative or ER+ breast cancer cells, the AHR was shown to regulate aldehyde dehydrogenase (ALDH), which, like ABCG2, is associated with chemotherapy export." (PMID 33396563, 2020). "Our study was performed to explore the mechanism by which emodin acts on breast cancer cells through a comprehensive network pharmacology and experimental approach, which proved that emodin can activate AhR to inhibit the proliferation of MCF-7 cells and promote apoptosis." (PMID 33542691, 2020). "However, like other receptors, relatively non-toxic SAhRMs which exhibit tissue-specific AhR agonist or antagonist activities have been developed including the AhR-active drug “aminoflavone” which has been in clinical trials for breast cancer." (PMID 32731514, 2020). "In addition, the presence of high levels of AHR correlated to poor overall survival in breast cancer patients and its activation promotes invasion of clear cell renal cell carcinoma." (PMID 32907554, 2020). "In breast cancer, high levels of AhR expression were inversely correlated with grading." (PMID 31212758, 2019). "Altogether, our results indicate that 3MC may engage both GPER and AHR transduction pathways toward breast cancer progression." (PMID 31370872, 2019). "This trend was in line with previous reports documenting that constitutively active AHR in rodent and human mammary tumors associated with elevated CYP1B1, but not CYP1A1 or mRNA." (PMID 31652854, 2019). "Thus, although multiple factors contribute to expression of the invasion-associated genes analyzed here, our data are consistent with a role for the AHR in influencing their expression in a significant fraction of primary human breast cancers." (PMID 29735912, 2018). "Another novel finding of this study is that BRCA1 expression is strongly associated with the high AHR-expressing ERα-negative subpopulation, indicating a possible implication of AHR in DNA repair in ERα-negative breast cancers." (PMID 29320557, 2018). "Activation of AhR induces proteasome-dependent ERα degradation in human breast cancer cells." (PMID 30314280, 2018). "In addition to being responsive to exogenous ligands, the AHR has a constitutive activity that modulates gene expression in breast cancer." (PMID 30103560, 2018). "Importantly, a significant fraction of those genes was changed in a direction that suggests decrease in doxorubicin-mediated inhibition of the aryl hydrocarbon receptor signaling, a pathway known to drive breast cancer progression." (PMID 29540829, 2018). "Estrogen receptor-negative (ER−) cells were used since there remains an unmet medical need for targeted therapeutics for ER- breast cancers and since interpretation of outcomes involving the AHR in ER+ cells is confounded by the well-established cross-talk between the AHR and ER signaling pathways." (PMID 29735912, 2018). "The breast cancer ER status likely influences AhR activity involved in these signaling pathways." (PMID 29320557, 2018). "The ER status of breast cancer cells and tumors is known to influence AHR transcriptional activity." (PMID 29320557, 2018). "The data also support the hypothesis that AHR downregulation would be beneficial in human breast cancer." (PMID 29735912, 2018). "Similarly, triple negative (ER-/PR-/Her2-) human breast cancer cells exhibit elevated TDO2 expression that is dependent on the AHR." (PMID 30501068, 2018). "Our findings documenting AhR expression levels may contribute to targeting AhR for breast cancer therapy." (PMID 29320557, 2018). "Many studies have suggested cross-talk between AhR and ERα in ERα-positive breast cancer cells." (PMID 29320557, 2018).
breast carcinoma (continued). "AHR-dependent upregulation of MMP1 may be a characteristic that breast cancer cells share with melanoma and gastric tumor cells and with TCDD-treated normal human keratinocytes." (PMID 29735912, 2018). "Furthermore, the AhR has been shown to bind to NF-κB subunit RelB and that interaction of RelB and AhR in the breast cancer cell lines MCF-7 and MDA-MB-436 induced IL-8 expression." (PMID 29487603, 2018). "However, activation of AhR inhibits invasive and metastatic features of human breast cancer cells and promotes breast cancer cell differentiation." (PMID 29320557, 2018). "TGFB1, TNF, IL1B and IL6 are inhibited by ligand-bound AhR in ERα-positive breast cancer cells." (PMID 29320557, 2018). "Based on this observation, it was suggested that AhR is a tumor suppressor in human breast cancer." (PMID 29189985, 2018). "In addition, recent studies from our laboratory and others have demonstrated the pivotal role of AhR/CYP1A1 in development of breast cancer." (PMID 28103884, 2017). "Furthermore, CHiP seq experiments in MCF-7 human breast cancer cells treated with the exogenous AHR agonist TCDD (2,3,7,8-tetrachlorodibenzo-p-dioxin) identified AHR interactions with DNA from genes in the triglyceride pathway." (PMID 28265266, 2017). "For example, AHR agonists may inhibit growth in ER+ breast cancers in part through AHR-mediated down-regulation of ER expression or activity." (PMID 26984638, 2016). "In fact, functional interactions between AhR and miR-335 have been described in breast cancer." (PMID 27243009, 2016). "Finally, a limited number of previous studies have addressed the role of the AHR in breast cancer stem cell generation." (PMID 26984638, 2016). "Furthermore, a predominance of nuclear AHR in primary human breast cancers, but not in normal breast tissue, supports the conclusion that the AHR is constitutively active in primary cancers as well." (PMID 26984638, 2016). "Consequently, the use of selective modulators of the AhR (SAhRMs) has been proposed in breast cancer therapy." (PMID 26715507, 2015). "This study reports that rat mammary tumors induced with the AhR-agonist 7,12-dimethyl-benzo(a)anthracene (DMBA) had augmented CpG methylation of the Brca-1 gene; higher expression of Ahr, Cyp1b, and proliferation markers (Cdk4, Ccnd1); and diminished expression of BRCA-1 and ERα." (PMID 26715507, 2015). "However, this compound also exhibited AHR agonist activity and activated inhibitory AHR-ERα crosstalk in breast cancer cells and decreased mammary tumor growth in vivo." (PMID 25011475, 2014). "In the present study we sought to identify alterations of global gene expression in MDA-MB-231 cells following stable AhR knockdown in order to determine which of the genes and signaling pathways involved in breast cancer progression are affected by the elevated AhR levels." (PMID 24932473, 2014). "As many of these genes are multifunctional and the primary cause for cellular transformation is aberrant expression of genes/proteins, this study sheds light on molecular mechanisms through which AhR overexpression may influence breast cancer progression." (PMID 24932473, 2014). "The protein–protein interaction network (PIN) provides insight on how AhR expression might influence breast cancer." (PMID 24932473, 2014). "In breast cancer, elevated and constitutively active levels of AhR were found in advanced human breast tumors and breast cancer cell lines, with a strong correlation between expression of AhR and the degree of the tumor malignancy." (PMID 24932473, 2014). "Based on these phenotypic changes, we hypothesize that the elevated levels of AhR in advanced breast cancer are driving signaling pathways involved in cell survival, adhesion and invasiveness." (PMID 24932473, 2014).
breast carcinoma (continued). "We previously reported that stable knockdown of AhR decreased the tumorigenic properties of the highly metastatic MDA-MB-231 breast cancer cell line; whereas ectopic overexpression of AhR was sufficient to transform immortalized human mammary epithelial cells to exhibit malignant phenotypes." (PMID 24932473, 2014). "The aryl hydrocarbon receptor (AhR), a transcription factor that is best known for its role in mediating the toxic responses elicited by poly aromatic hydrocarbons as well as many other environmental factors; is also involved in breast cancer progression." (PMID 24932473, 2014). "Among the eight compounds, only omeprazole inhibited MDA-MB-231 breast cancer cell invasion and this response could be reversed, in part, by AHR antagonists or by knockdown of the AHR by RNA interference (RNAi)." (PMID 25011475, 2014). "We examined the expression of ERα and AhR in four human breast cancer cell lines." (PMID 24885022, 2014). "In these human and rodent mammary tumors, AhR was also over-expressed and constitutively active." (PMID 24755659, 2014). "Later studies revealed that TCDD and other AhR ligands inhibit cellular proliferation of human breast cancer cell lines, as well as DMBA-induced mammary tumors in rats, and, consequently, these observations highlight a possible functional crosstalk between AhR and ERα signaling." (PMID 25048790, 2014). "Increased understanding of the role of these potential endogenous ligands in breast cancer cells could provide additional insights on the role of AhR in mediating breast cancer progression." (PMID 25068070, 2013). "We further investigated the potential of AhR as a stage specific marker of breast cancer." (PMID 25068070, 2013). "Although this dual double-edge role may make AhR a rather difficult target for breast cancer therapy, the focus will be on the unique aspects of its biology that is more specific to breast cancer invasion and metastasis." (PMID 25068070, 2013). "The AhR may play a role in breast development in utero, during pregnancy and is also reported to play a critical role in breast cancer development." (PMID 25068070, 2013). "The development of selective AhR modulator (SAhRM) could prove beneficial in preventing breast cancer progression and/or metastasis." (PMID 25068070, 2013). "Given these prior reports, the purpose of this study was to examine the possibility that specific ligand-activated AHR inhibits mitogenic adipokine signaling in human MCF-7 breast cancer cells and to provide preliminary insights into the mechanism by which this occurs." (PMID 24171117, 2013). "The constitutive expression and cellular localization of AhR were assessed by western blot analyses and immunofluorescence staining in 6 human breast cancer cell lines representing AFP464-sensitive (MCF-7, SUM44, MDA-MB-468, and BT20) and -resistant (Hs578T and MDA-MB-231) cell lines." (PMID 24058584, 2013). "Whether specific ligand-activated AHR inhibits adipokine stimulated breast cancer cell proliferation and the potential mechanisms by which this could occur have not been investigated." (PMID 24171117, 2013). "Consistent with other investigators' observations in breast cancer cells, we observed the recruitment of AHR and ARNT on the human CYP1A1 enhancer in a TCDD-dependent fashion and ERα was greatly enriched only after treatment with a combination of 2 nM TCDD and 10 nM E2." (PMID 22235307, 2012). "Thus, immunohistological analysis of AhR should also be considered as a tool in the upcoming Phase II trials in breast cancer to select patients that are most likely to benefit from AF treatment." (PMID 22295239, 2011). "Pancreatic (70%) and breast cancers (46%) showed the highest percentage of cytoplasmic AhR." (PMID 22295239, 2011). "This offers a new potential treatment strategy for breast cancers with intact AhR signaling." (PMID 22295239, 2011). "This is a new treatment strategy for breast cancers with intact AhR signaling." (PMID 22295239, 2011).
breast carcinoma (continued). "Whether all breast cancer cell types are sensitive to tranilast warrants further investigation, but studies with other AHR agonists such as TCDD suggest this will be the case." (PMID 21072210, 2010). "Furthermore, the same group discovered that several in vitro cultured mouse as well as human breast cancer cell lines show high levels of expression of AhR." (PMID 19604390, 2009). "Similarly, high levels of nuclear AhR were observed in human Hs578T cells and in several other human breast cancer cell lines (for example, CAMA-1, MCF-7, and MDA MB 231; data not shown)." (PMID 16569260, 2006). "Indeed, the potential role of the AhR in tumorigenesis has inspired the possible use of AhR modulators for breast cancer therapy." (PMID 16569260, 2006). "Therefore, the complexity of crosstalk between AhR and ERα requires consideration in searching for new chemopreventive or therapeutic agents, particularly for treating hormone-dependent cancers such as breast cancer." (PMID 40807256, 2025). "Thus, metformin decreases CYP1A1 and CYP1B1 expression in breast cancer cells by suppressing the AhR signaling pathway and may act as a potential chemopreventive agent against CYP1B1- and CYP1A1-mediated carcinogenesis and cancer progression." (PMID 41440753, 2025). "In this regard, TCDD-induced EGFR expression changes in breast cancer cells were associated with downstream signaling activation and apoptosis inhibition, whereas this effect was reversed by an AhR antagonist, indicating a tumor-promoting effect of EGFR-mediated AhR signaling." (PMID 39211042, 2024). "In addition to IDO1, breast cancer may show the concurrent expression of other immunosuppressive and tumor-promoting factors, which can even involve the kynurenine-AHR-axis." (PMID 39061522, 2024). "Moreover, the acrylonitrile (Z)-2(3,4-dichlorophenyl)-3-(1H-pyrrol-2-yl) (ANI-7) and analogues are AhR agonists that inhibit proliferation in broad panel of breast cancer cell lines including MDA-MB-231, MDA-MB-468, ZR-75-1, SKBR3, MCF-7, BT474, T47D, and BT20." (PMID 37241719, 2023). "However, the use of AhR agonists as anticancer agents against breast cancer may lead to the down-regulation of SLCOs, and, therefore, the combination with OATP/SLCO substrate drugs should be investigated thoroughly." (PMID 36839686, 2023). "We previously determined that the aryl hydrocarbon receptor (AhR) agonist aminoflavone (AF) inhibits the expression of the CSC biomarker α6-integrin (ITGA6) to disrupt the formation of luminal (hormone receptor-positive) mammospheres (3D breast cancer spheroids)." (PMID 35694715, 2022). "Moreover, Hanieh, (2015; 2016) assessed the AhR-miR-212/132 axis in breast cancer cell lines and confirmed the anti-metastatic properties of the miRNA cluster through suppression of SOX-4, which inversely is a pro-metastatic factor and has binding sites for miR-212/132 on the 3′ UTR region." (PMID 34746229, 2021). "In addition, a novel naphthalimide (NAP‐6) could selectively target breast cancer cells by activating the arylhydrocarbon receptor (AhR) pathway." (PMID 34448532, 2021). "Thus, the reported ability of DEP to act as an AhR agonist could sustain the hypothesis that DEP interference on estrogenic signaling in breast cancer cells may occur by stimulating cellular E2 synthesis." (PMID 34678933, 2021). "Therefore, we chose AhR as the key target of emodin in breast cancer for more in-depth research." (PMID 33542691, 2020). "However, there are few studies on emodin-mediated regulation of the AhR target of breast cancer." (PMID 33542691, 2020). "Further, AHR hyper-activation with the endogenous ligand FICZ induced migration and invasion-associated (Snai1, Twist1, Twist2, Tgfb1, Vim) and stem cell-associated (Notch1, Notch2, Bmi1, Nanog, Sox2, Dppa3) genes in triple negative ALDHhigh breast cancer CSCs." (PMID 33396563, 2020).
breast carcinoma (continued). "We observed that the AHR protein levels were significantly increased to about 1.5- to 1.7-fold in the presence of 40 μM CQ for six hours in a variety of cancer cell types—namely liver cancer cell line Hep3B, lung cancer cell line A549, and two breast cancer cell lines T-47D and MDA-MB-468." (PMID 32414129, 2020). "Evidence from our meta-analysis suggests that AhR rs2066853 polymorphism is not a risk factor for cancer either in the overall population, Caucasians, Asians, or Chinese, and this polymorphism is not a risk factor for lung cancer or breast cancer." (PMID 33278884, 2020). "That said, Paclitaxel and Adriamycin have been shown to enhance AHR expression in MDA-MB-231 breast cancer cells and AHR activity in cardiomyocytes, results that one would have expected would lead to a reduction in efficacy of a chemotherapeutic plus AHR inhibitor regimen." (PMID 33396563, 2020). "Hence, prominent ligands of the AhR behave also as inducers of CYP 1A1 activity, such as 2,3,7,8–tetrachlorodibenzo-p-dioxin (TCDD) and benzo[a]pyrene (B[a]P), which are suggested to be involved in increased breast cancer risk." (PMID 32659980, 2020). "This cooperative action, which promotes the dissociation of AHR from the cytosolic chaperone complex and its subsequent nuclear translocation, may have important implications toward the development of various malignancies including breast cancer." (PMID 31370872, 2019). "In addition, hyperactivation of the AhR with exogenous and endogenous ligands may induce different signaling pathways and lead to reduced invasion of breast cancer cells." (PMID 29487603, 2018). "However, relatively little is known about the role of AhR in human breast cancers." (PMID 29320557, 2018). "Consistently, AhR knockdown impaired the protective effects of receptor expression and rescued cell motility and invasion, suggesting that AhR-induced differentiation could be a valuable tool in breast cancer treatment." (PMID 27243009, 2016). "Our recent reports indicate that pharmacological aryl hydrocarbon receptor (AHR) ligands inhibit breast cancer cell responses to IGFs, suggesting that targeting AHR may have benefit in cancers whose proliferation and survival are dependent on insulin/IGF signaling." (PMID 25699021, 2015). "Thus, omeprazole may have potential clinical applications for inhibition of breast cancer metastasis due, in part, to its AHR agonist activity." (PMID 25011475, 2014). "AHR-active pharmaceuticals such as omeprazole that decrease breast cancer cell invasion and metastasis may have important clinical applications for late stage breast cancer chemotherapy." (PMID 25011475, 2014). "In this study, we initially used the same set of AHR-active pharmaceuticals in triple-negative MDA-MB-231 cells with a primary objective of identifying a known pharmaceutical that may be effective for inhibiting breast cancer metastasis." (PMID 25011475, 2014). "Interestingly, we found that AF sensitivity could be uncoupled from AhR responsiveness as exemplified in a human breast cancer cell line, Cal51." (PMID 24885022, 2014). "Consequently, exposure to AhR agonists could have different outcomes making it challenging to show direct effects of pollutants on breast cancer incidence." (PMID 25257533, 2014). "As better understanding of AhR activity in breast cancer has shed light on some aspects of AhR signaling, identifying downstream targets will constitute even better option for targeted therapy, given the essential role of AhR in maintenance physiological functions." (PMID 25068070, 2013). "Therefore, it is reasonable to hypothesize that AhR up-regulation is a general characteristic of mammary tumors and that it influences their growth." (PMID 16569260, 2006). "In breast cancer, KYNA binds to AhR to promote IL‐6 expression (enhanced binding of AhR with RelB leads to increased IL‐6 transcription)." (PMID 40103267, 2025).